BRAF (B-Raf proto-oncogene, serine/threonine kinase)
Diseases named in the same sentence as BRAF in open-access papers (continued):
Sharing a sentence is not in itself a finding about the gene and the disease.
melanoma (continued). "In this study, as an extension to our previous work on head and neck mucosal melanomas, we aimed to investigate the BRAF, NRAS, KIT, TERT and GNAQ/GNA11 mutation status of 15 AMs, as well as their clinicopathologic features." (PMID 35642348, 2023). "The selected 12 drugs were then tested in a cell viability assay on NRAS (IPC298, SKMel30) and BRAF (A375, 624Mel) mutated melanoma cell lines and the IC50 values for each drug and cell line were computed." (PMID 37495601, 2023). "It is interesting to note that different melanoma subtypes are characterized by different frequencies of BRAF and NRAS mutations." (PMID 37627054, 2023). "In melanoma, the most common mutation is in the B-raf proto-oncogene serine/threonine kinase (BRAF) gene." (PMID 37445615, 2023). "CDK12 plays an important role in the growth of cancers driven by dysregulated transcription factors, such as MYC (neuroblastoma) and the EWS–FLI1 fusion (Ewing sarcoma), or in melanoma driven by activating mutations in BRAF." (PMID 38104154, 2023). "In oligoprogressive melanoma patients with BRAF mutations, target therapy can be combined with loco-regional radiotherapy (RT)." (PMID 36830931, 2023). "Preclinical studies show that activation of AMP kinase by phenformin can augment the cytotoxic effect and RAF inhibitors in BRAF V600-mutated melanoma." (PMID 37930123, 2023). "In melanomas, this dysregulation is often caused by activating mutations in the BRAF and NRAS genes." (PMID 37235843, 2023). "Noticeably, trametinib, dabrafenib, and binimetinib have a PIP in the same adult indication (melanoma with BRAF mutation), but other indications targeted by the BRAF mutation of interest for pediatric tumors were also added." (PMID 37521350, 2023). "Regarding multivariate analysis, age (p < 0.001), presence of melanoma ulceration (p = 0.006), unspecified and other histologic subtype of melanoma (p = 0.015) and positive BRAF mutation (p = 0.040) were correlated with poor OS." (PMID 37345002, 2023). "Options for frontline therapy in progressed patients with BRAF-mutated melanoma include checkpoint inhibition and BRAF/MEK inhibition; however, no consensus has been reached on treatment choice and correct sequencing of therapy." (PMID 36995534, 2023). "Some of the most commonly occurring somatic alterations in melanoma include mutations in the BRAF, NRAS, and KIT genes." (PMID 37504268, 2023). "NRAS- and NRAS-BRAF-co-mutated melanomas have a less favorable prognosis than BRAF-mutated ones as there are no target therapies for NRAS mutations." (PMID 37958863, 2023). "Inhibitors such as trametinib, cobimetinib, and binimetinib have been approved by the U.S. Food and Drug Administration for the treatment of BRAF V600E-mutated melanoma, non-small cell lung cancer, and anaplastic thyroid cancer." (PMID 37097377, 2023). "Recent findings show that the prevalence of ERBB4 mutations in melanoma is relatively low compared to other genetic alterations like BRAF or NRAS mutations." (PMID 37504268, 2023). "More recently, therapy became more effective owing to the use of rapidly accelerated fibrosarcoma B (BRAF) and mitogen-activated protein kinase (MEK) inhibitors, which are active against BRAF-mutated melanomas." (PMID 36986798, 2023). "Malignant melanoma is the most lethal form of skin cancer which shows BRAF mutation in 50% of patients." (PMID 37534247, 2023). "Approximately 40% to 60% of malignant melanoma cases carry mutations in BRAF, which is the most frequent mutation event in melanoma." (PMID 37513949, 2023). "Although these agents were effective in approximately half of the patients with BRAF-mutated melanoma, most patients developed secondary resistance in a relatively short period." (PMID 37446286, 2023).
melanoma (continued). "Two of them demonstrated that, after treatment with two commonly used BRAF inhibitors (vemurafenib and dabrafenib), the EVs released by resistant melanoma cells contained factors linked to melanoma resistance and BRAF inhibitors, such as miR211-5p and PDGFR." (PMID 36831417, 2023). "Considering the role of BRAF mutations in the pathogenesis of melanoma, treatments mostly target BRAF, MAPK, and ERK in order to dampen the deleterious effects of the constitutively active BRAF/MEK/ERK cascade." (PMID 36672229, 2023). "MAP2K1 mutations are enriched in BRAF-mutant melanoma and function as an innate or adaptive resistance mechanism to BRAF inhibition." (PMID 36901951, 2023). "Increased transcriptional levels of SOX10 are suggested to desensitize BRAF‐mutant melanoma to MAPK inhibition, however, loss of SOX10 has also been shown to drive acquired resistance." (PMID 36251678, 2023). "Systemic treatment of malignant melanoma depends on potential mutations, such as BRAF, NRAS, and c-kit mutations, responsive for current therapeutics." (PMID 36680624, 2023). "The BRAF V600E mutation activates cell growth, aiding targeted therapy selection in melanoma patients." (PMID 38202898, 2023). "We demonstrated that TERT overexpression in BRAF-mutated melanoma cells reduced sensitivity to BRAF and MEK independently of TERT’s telomer maintenance activity." (PMID 37296851, 2023). "In Mexico, studies identified BRAF V600E variant frequencies in primary melanoma studies ranging from 6·4% (3/47 patients in Mexico City) to 73·0% (24/33 in Northeast Mexico)." (PMID 36998456, 2023). "Antitumor activity of tovorafenib in BRAF-mutated melanoma was promising and justifies continued clinical development across multiple settings." (PMID 37219686, 2023). "A 19-year-old male presented with BRAF V600K-mutated stage IIID melanoma of the scalp (T4b [ulcerated, Breslow thickness 4.5 mm], N3a [7/48 lymph nodes], M0)." (PMID 37338166, 2023). "This medicine was developed for the treatment of late-stage melanoma to cause apoptosis in melanoma cells by interrupting the BRAF/MEK/ERK pathway only in the presence of the common BRAFV600E mutation." (PMID 37446932, 2023). "Molecularly, melanomas harbor somatic ‘driver mutations’ that are mutually exclusive: 50% present gain‐of‐function BRAF mutations, while another 25% exhibit NRAS mutations." (PMID 36744297, 2023). "The most frequently mutated positions in our cohort of 524 primary melanomas included nucleotides in well‐known driver genes such as BRAF, NRAS and TERT, and a similar frequency of RQCD1 p.P131L mutations has been described in another primary melanoma cohort." (PMID 36219477, 2023). "The challenges to providing adequate and effective diagnosis and treatment for patients with BRAF-mutated melanoma are discussed, and recommendations on overcoming these barriers will be provided." (PMID 36998456, 2023). "Selected experiments on cells isolated from a BRAF-mutated melanoma patient were performed with vemurafenib, a BRAF inhibitor." (PMID 37175742, 2023). "In a single-institution cohort of 459 patients with melanoma in Barretos, Brazil, 34% carried a BRAF mutation." (PMID 36998456, 2023). "Larger clinical studies are ongoing to confirm the efficacy and safety of this sequencing strategy for treating BRAF-mutated melanoma with immunotherapy followed by targeted therapy." (PMID 36995534, 2023). "The success of targeted therapies in BRAF-mutated melanoma has led to the recommendation that patients with advanced disease and at high relapse risk be screened for V600 mutations to help guide therapeutic decision making." (PMID 36998456, 2023). "The BRAF mutation affects serine-threonine kinase BRAF and is found in ~40–60% of melanoma, while the NRAS mutation affects the RAS protein responsible for activating the signaling pathways that control cell proliferation, differentiation and survival." (PMID 37627116, 2023).
melanoma (continued). "All BRAF mutant malignant melanoma patients were confirmed with the SensiScreen® FFPE BRAF qPCR Assay and additional four new mutations in the malignant melanoma cohort were identified." (PMID 36758042, 2023). "BRAF-mutated melanomas have a significantly better prognosis than NRAS-mutated or BRAF-NRAS-co-mutated melanomas." (PMID 37373134, 2023). "BRAF non-V600 mutated melanomas are rare, and data are scarce concerning the best therapeutic options." (PMID 37373134, 2023). "The development of resistance to BRAF/MEK inhibitors was also monitored by the detection of BRAF splicing variants in the plasma of melanoma patients with objective response followed by disease progression." (PMID 36674479, 2023). "One of the essential genes implicated in nevi and melanoma development is the BRAF gene, a human proto-oncogene located on the long arm of chromosome 7 (7q34)." (PMID 36737739, 2023). "The BRAF inhibitors vemurafenib and dabrafenib were approved for the treatment of metastatic and unresectable BRAF-mutated melanoma in 2011 and 2013, respectively." (PMID 37446286, 2023). "Only a small number of mucosal melanoma patients which harbor mutations in BRAF or KIT benefit from targeted therapy." (PMID 37831226, 2023). "The synergistic antitumor effect of vorinostat in combination with BRAF inhibitors and the ability of vorinostat to eliminate BRAF inhibitor-resistant and senescent cells was reported in BRAF-mutated melanoma cells." (PMID 38258065, 2023). "More than half of the melanoma tumors harbor an activating mutation in BRAF, a serine/threonine kinase protein, which enhances tumor proliferation and invasion, hence targeted BRAF inhibitor therapies such as Vemurafenib have been developed with high efficacy." (PMID 37013489, 2023). "Melanoma associated with a low level of UV radiation exposure frequently carry a BRAF mutation, which is present in approximately 50% of cutaneous melanomas." (PMID 37296851, 2023). "We will also describe the mechanisms responsible for resistance to targeted therapies in BRAF-mutated melanoma." (PMID 37627054, 2023). "Two cases of patients with advanced melanoma controlled by long-term MEK inhibitors or a combination of BRAF and MEK inhibitors who developed fractures associated with severe osteopenia." (PMID 36761953, 2023). "Axl and MerTK are closely related RTKs that have both been associated with drug resistance and immunological resistance in melanoma Antibody-mediated inhibition of Axl appeared to restore patient susceptibility to BRAF inhibitors." (PMID 38067178, 2023). "Targeted therapy with BRAF‐ and MEK‐Inhibitors (BRAFi and MEKi) provides an excellent therapeutic option for patients with malignant melanomas harbouring a BRAF‐Mutation." (PMID 36751314, 2023). "BRAF is mutated in 66% of malignant melanomas, and the mutation occurs in the kinase domain by the substitution of valine for glutamate at position 600 (V600E) in 80% of cases." (PMID 37371032, 2023). "BRAF is the most commonly mutated gene involved in the development of melanomas, but other RAS superfamily members (HRAS, NRAS, and KRAS) also contribute to the initiation, progression, aggressiveness, and response to the therapy of cutaneous melanoma." (PMID 36765834, 2023). "The identification of BRAF V600 mutation in multiple cancers beyond melanoma and the development of combined BRAF and MEK targeting agents have altered the landscape of tissue-agnostic precision oncology therapies with an impact on survival outcomes." (PMID 37231247, 2023). "Similar to our system, in metastatic melanoma cells characterized by BRAF mutations, resistance to MEK and BRAF inhibitors is mediated by MAPK rebound, and more specifically, Erk re-activation is mediated by Pak134." (PMID 37258566, 2023). "The BRAF inhibitors vemurafenib and dabrafenib were the first to be approved for the treatment of BRAF-mutated melanoma." (PMID 36836846, 2023).
melanoma (continued). "Though not previously studied in UM, 4-PBA, a selective ER stress inhibitor, has been proven to be effective for BRAF-mutated melanoma." (PMID 37709773, 2023). "Given that the BRAF-activating mutations have been identified as the most common genetic variation in melanoma, BRAF inhibitors can increase the susceptibility of melanoma cells to ferroptosis." (PMID 37996827, 2023). "On these bases, several randomized clinical trials evaluated the efficacy of these combinations in the frontline setting for BRAF-mutated melanoma patients." (PMID 36995534, 2023). "BRAF mutations are present in more than 50% of melanomas, with BRAFV600E being the most prevalent mutation type." (PMID 37745303, 2023). "The general approach described here is applicable for investigating Ras functions in other cancer cell line models characterized by driver kinase mutations such as EGFR-mutant lung adenocarcinoma and BRAF-mutant melanoma cell lines." (PMID 37681415, 2023). "For example, dabrafenib targets mutated BRAF proteins and is used in the treatment of CRC and melanoma patients harbouring BRAF V600E mutations." (PMID 37751451, 2023). "Melanoma BRAF mutations are nearly all missense variants (98.65%) as reported in the COSMIC (Catalogue of Somatic Mutation in Cancer) database." (PMID 37627054, 2023). "In our previous work, we noticed decreasing levels of EZH2 in BRAFV600E-mutated melanoma cells treated with vemurafenib, while cells resistant to BRAF inhibitors showed an unchanged expression of EZH2 upon treatment with vemurafenib." (PMID 36768289, 2023). "In melanoma, in which BRAF mutations are more frequent, the BRAF inhibitors vemurafenib or dabrafenib have shown high response rates and have improved the survival of patients dramatically." (PMID 36900221, 2023). "Melanocytic nevi induced by BRAF mutations gradually remain senescent for decades, preventing their progression into melanoma." (PMID 36945046, 2023). "RSK directly phosphorylates PFKFB2 to increase PFKFB2 activity and glycolysis, which accelerates the growth of BRAF‐mutated melanoma." (PMID 37143582, 2023). "Most cases of melanoma are sporadic while the most frequent somatic mutation occurs in the 600th codon of the gene BRAF (50% of cases)." (PMID 36604647, 2023). "BRAF mutations are widely described in melanoma and known to be linked to worse prognosis and chemoresistance." (PMID 37794430, 2023). "Results showed that the ERK phosphorylation level of BRAF-mutated melanoma A375 cells decreased in a dose-dependent manner and reached almost completely blocked under treatment of tunlametinib at 100 nM." (PMID 37808191, 2023). "These recent clinical trials have explored several aspects of sequencing and combining the principle therapeutic approaches for BRAF mutated melanoma." (PMID 37543586, 2023). "Oncogenic BRAF mutations have been widely described in melanomas and promote tumour progression and chemoresistance." (PMID 37298104, 2023). "BRAF V600E, the most common BRAF mutation in melanoma (40–50% of cases), occurs when a single amino acid (valine) is replaced with another amino acid (glutamic acid) at position 600 in the BRAF protein." (PMID 37504268, 2023). "These analyses’ observations suggest a strong association between the 13-risk signature and the occurrence of resistance to BRAF/MEK targeted treatment in melanoma patients." (PMID 37176114, 2023). "In this review, we will discuss various biological aspects of melanoma related to BRAF mutation, including circulating and tissue biomarkers." (PMID 37627054, 2023). "In a phase II basket trial of the BRAF inhibitor vemurafenib in non-melanoma BRAF V600 mutation-positive solid tumors, two NEC patients had PFS of 7.8 months and 5.7 months, respectively." (PMID 37422534, 2023). "In advanced melanoma, the liquid biopsy can improve the identification of BRAF and receptor tyrosine kinase (KIT) mutations for targeted therapy choice." (PMID 36937316, 2023).
melanoma (continued). "BRAF mutations represent the most prevalent oncogenic event in melanoma, resulting in constitutive activation of the BRAF-MEK-ERK MAPK pathway." (PMID 37760480, 2023). "The Cancer Genome Atlas (TCGA) has identified BRAF mutations in many tumour types, especially melanomas, thyroid cancers, lung cancers." (PMID 37542343, 2023). "In 2014 the combined treatment of trametinib and dabrafenib, and later in 2020, the combination of atezolizumab with cobimetinib and vemurafenib was approved by FDA for patients with BRAF V600 mutation-positive melanoma." (PMID 37568193, 2023). "The relevance of this pathway is underlined by the fact that hyperactivity of the ERKs through mutations in NRAS, its negative regulator NF1, or its downstream effector BRAF are causally related to ~75% of sporadic melanomas." (PMID 37762683, 2023). "Dabrafenib (Tafinlar®) is an inhibitor for the b-Raf enzyme used for cancers associated with the mutated gene BRAF, such as BRAF-mutated melanoma." (PMID 37959874, 2023). "BRAF mutation plays an important role in the pathogenesis and progression of melanoma and is correlated to the prognosis of melanoma patients." (PMID 37205993, 2023). "Other molecular results included three melanomas: two with a BRAF V600 mutation and one with native BRAF V600 and one sarcoma." (PMID 37998611, 2023). "The different BRAF mutations that have been identified in patients with solid tumours (malignant melanomas, colorectal or non‐small‐cell lung cancers) are mainly located either in exon 11 or 15 of BRAF." (PMID 37530550, 2023). "BRAF-V600E mutations are present in most nevus, so other lesions would have to occur to develop melanoma." (PMID 36978957, 2023). "Because melanoma therapies can cause end-organ toxicities (e.g. immune-related adverse events impacting many different organs, and BRAF/MEK inhibitors causing cardiomyopathy), we assessed organ function in relation to systemic therapy." (PMID 36949413, 2023). "A patient in her late 60s presented with a BRAF V600E mutated melanoma with cerebral, pulmonary, hepatic, adrenal, and bone metastases." (PMID 37728439, 2023). "Vemurafenib was approved for treatment of metastatic and advanced BRAF-mutated melanoma as the first selective BRAF kinase inhibitor." (PMID 37620300, 2023). "Determining BRAF mutation status is essential for the therapeutic management of melanomas, particularly those of the skin." (PMID 37649946, 2023). "In humans, mutations in BRAF frequently occur in various tumour types, such as melanoma, thyroid carcinoma, and colorectal carcinoma, and it has been shown that the BRAF mutation can show inter- and intratumoral heterogeneity." (PMID 37570213, 2023). "BRAF inhibitors initially showed significant survival benefits as monotherapy in BRAF-mutated solid tumors like melanoma." (PMID 38202120, 2023). "The most current clinical data support the use of ICI as the preferred first-line treatment for BRAF-mutated melanoma." (PMID 37568570, 2023). "The BRAFV600E mutation is found only in about 50% of melanoma and this fact limits the use of BRAF inhibitors (BRAFi)." (PMID 37608347, 2023). "BRAF/MEK therapy and anti-PD-1 therapy have shown better recurrence-free survival of stage III melanoma in patients with BRAF V600 mutations in clinical trials." (PMID 36672358, 2023). "A great proportion of BRAF V600E mutations (74%) were also identified in nevi-related melanomas and 68% of carriers of BRAF V600E had a melanoma in areas of low sun exposure, such as the trunk, and sun-protected areas of upper and lower extremities." (PMID 36765773, 2023). "The results showed that CYTL1 was a pro-oncogenic factor in both melanoma and BRAF-mutated melanoma, and its high expression significantly suppressed patients’ OS and DFS." (PMID 37745303, 2023). "They studied its anticancer profile and its potential as a drug against melanoma with mutation in the BRAF gene, the dominant form of this disease, and with minimal effect on fibroblasts." (PMID 37836558, 2023).